NOS3 (nitric oxide synthase 3)
Diseases named in the same sentence as NOS3 in open-access papers (continued):
Sharing a sentence is not in itself a finding about the gene and the disease.
Hypertension (243 papers, 2006 to 2026). The presence of chronic increased pressure in the systemic arterial system. "NOS3 genetic polymorphisms have been associated with various diseases, such as hypertension, chronic kidney disease, coronary artery disease, sickle cell anemia, subarachnoid hemorrhage, and diabetic retinopathy." (PMID 40142738, 2025). "Nos3-/- mice with myeloid MR deficiency had equivalent diabetes and hypertension as myeloid MR intact controls but were protected against cardiac and renal function impairment." (PMID 41332229, 2025). "The critical role of eNOS in controlling vascular tone was documented by findings that pharmacological inhibition of NOS causes hypertension and deletion of NOS3 results in high blood pressure." (PMID 39917079, 2025). "Mice genetically deficient in myeloid MR were crossed onto mice genetically deficient in Nos3 which spontaneously develop hypertension, have increased susceptibility to diabetic tissue injury and display more rapid progression of cardiac and kidney disease." (PMID 41332229, 2025). "Several polymorphisms in NOS3 have been reported in connection with hypertension and antihypertensive drug response." (PMID 40534840, 2025). "It has been observed that anti-VEGFR-2 antibody treatment in mice caused hypertension due to reduced NOS3 and NOS1 expression in the kidney." (PMID 39011232, 2024). "It controls osteoclast activity and is involved in the exacerbated periodontitis caused by Nos3-/-related hypertension." (PMID 39219951, 2024). "Nevertheless, the fact that A-NOS3 KO mice have higher blood pressure despite less weight gain further underlines the importance of adipocyte NOS3 in diet-induced hypertension." (PMID 37897505, 2023). "In the present study, we investigated the impact of adipocyte-specific knockout of NOS3 on diet-induced hypertension and its associated vascular dysfunction and remodelling." (PMID 37897505, 2023). "The SNPs rs1799983 (c.894T>G, p.Asp298Glu), rs2070744 (c.-149 + 1691C>T), and rs61722009 in the NOS3 gene have been associated with the risk of hypertension among Algerians and Tunisians." (PMID 38633331, 2023). "NOS3 is known to be involved in NO synthesis, primarily in endothelial cells, and is linked to cardiovascular disorders such as hypertension, atherosclerosis, and diabetes mellitus." (PMID 37894904, 2023). "The effect of NOS3 gene polymorphism on hypertension and cardiovascular disease susceptibility has been extensively studied over the years." (PMID 36758021, 2023). "A T allele of NOS3 786C/T polymorphism increased the probability of bronchial asthma with comorbid essential hypertension in asthma patients." (PMID 37076778, 2023). "The single nucleotide polymorphisms rs1808593 and rs7830 of NOS3 gene are associated with essential hypertension in Guizhou ethnic populations." (PMID 36758021, 2023). "The symptoms observed in ApoE/NOS3−/− mice are caused by the loss of function of the ApoE and NOS3 genes, and the etiology of hypertension and atherosclerosis is often complicated and unclear in clinical practice." (PMID 36360235, 2022). "NOS3 was also considered a biomarker for pulmonary, essential, and pregnancy-associated hypertension." (PMID 35740428, 2022). "There was robust evidence demonstrating that the deficiency of NOS3 contributed to severe albuminuria, hypertension, mesangial expansion, the thickness of the glomerular basement membrane, and even glomerulosclerosis in different mouse models." (PMID 35855831, 2022). "In this way, the association between NOS3 polymorphisms and hypertension has been demonstrated in some studies." (PMID 33790801, 2021). "MetS includes dyslipidemia, hyperglycemia, hypertension, diabetes, and obesity, and there is an association between NOS3 gene polymorphisms and these features." (PMID 33995953, 2021). "In this study, there was a higher predisposition for hypertension in the presence of TT and AA genotypes for the NOS3 and IGFBP3 genes, respectively." (PMID 34001234, 2021).
Hypertension (continued). "A heterozygous mutation in Nos3 that results in haploinsufficiency of eNOS exacerbates hypertension and renal injury in SS rats." (PMID 33574248, 2021). "As for NOS3, this is a determinant polymorphism for the production of nitric oxide, with consequent implications for the development of atherosclerosis, hypertension, and Alzheimer's, with impact on cardiovascular risk and longevity." (PMID 32714484, 2020). "A hypertension related variant was also identified as a protein coding risk factor residing in the NOS3 gene." (PMID 31604968, 2019). "The association between NOS3 and EH has been widely studied, and the disruption of the gene leads to hypertension in mice." (PMID 29132319, 2017). "Additional knowledge of NOS3 gene polymorphisms and their role in hypertension will improve understanding of EH, its common predisposing factors, and potential treatment options." (PMID 29132319, 2017). "Some meta-analyses have shown the association between the NOS3 polymorphisms and hypertension, highlighting the intron 4b/a and 894G>T polymorphisms." (PMID 29104725, 2017). "Further, the a/a genotype of the NOS3 VNTR was shown to significantly increase the risk of developing hypertension in Indian men." (PMID 25340172, 2014). "The endothelial nitric oxide synthase (NOS3) gene is positively associated with hypertension and with inhibited vascular SMC proliferation and neointimal formation." (PMID 24174980, 2013). "Despite its pharmacogenetic potential, there are few data regarding the impact of NOS3 variants on the drug responses in hypertension treatments." (PMID 22470539, 2012). "Variants (polymorphisms) of the NOS3 gene have been investigated for association with preeclampsia and other disorders such as hypertension." (PMID 22051068, 2011). "G. D. Kitsios and E. Zintzaras reveal the protective effect of a haplotype of endothelial nitric oxide synthase gene (NOS3) for predisposition to hypertension." (PMID 21331162, 2011). "In conclusion, our genetic association study detected a protective effect of a rare NOS3 haplotype against hypertension." (PMID 20981307, 2010). "The endothelial nitric oxide synthase gene (NOS3) has been implicated in the development of hypertension, although the specific role of variants and haplotypes has not been clarified." (PMID 20981307, 2010). "Variants of the NOS3 gene located in the 7q35-q36 region have been investigated for association with hypertension and other cardiovascular disorders." (PMID 20981307, 2010). "This study evaluated relations between common genetic variants and haplotypes in the NOS3 gene with essential hypertension." (PMID 20981307, 2010). "Multivariate analysis revealed that the NOS3 GA+AA genotype, a FH of hypertension, and high pre-pregnancy BMI were strong independent risk factors for severe PIH among the subgroup with the PAI-1 5G/5G or 4G/5G genotypes." (PMID 19838007, 2009). "Certain strains of NOS3-deficient or sGCα1-deficient mice develop hypertension." (PMID 35862303, 2022). "Associations of endothelial nitric oxide synthase (NOS3) polymorphisms with hypertension and response to exercise training in prehypertensive and hypertensive older adult women remain unclear." (PMID 33790801, 2021). "Moreover, associations between DNp and DN/DNp and ABCA1 and NOS3 SNPs were common due to their influence on dyslipidemia and hypertension, which ultimately reduces kidney function." (PMID 35069435, 2021). "In addition to those presented in the previous sections, we found a methylation biomarker (cg21901847) within NOS3 that is associated with risk for early onset hypertension (β = −0.42, P = 5.3e−10) and CAD (β = 0.04, P = 7.5e−5)." (PMID 33574266, 2021). "Transgenic overexpression of fumarase in these rats increases NO and the ratio of L-arginine/citrulline in the renal outer medulla and abolishes hypertension and renal injury that may be attributed to Nos3 heterozygous mutation." (PMID 33574248, 2021).
Hypertension (continued). "For example, NOS3, which plays an important role in regulation of nitric oxide production, is associated with coronary artery disease, myocardial infarct, congestive heart failure, stroke, and hypertension." (PMID 29861771, 2018). "Association between CKD stages and hypertension stratified by NOS3 VNTR genotypes." (PMID 25340172, 2014). "Association of the NOS3 polymorphism (rs1799983) with DVT when stratified by hypertension status." (PMID 23922896, 2013). "Many reports have indicated association of NOS3 polymorphisms with increased occurrence of cardiovascular disease, including coronary artery disease, myocardial infarction, hypertension, and stroke." (PMID 22470539, 2012). "In a survey of all published association studies on the relation between the NOS3 gene polymorphisms and the risk of hypertension, a meta-analysis and subsequent sensitivity analyses supported an association only for the 4a/b polymorphism and hypertension." (PMID 20981307, 2010). "Our results indicate that genotype -786CC of the NOS3 gene increase the susceptibility to suffer resistant hypertension, which suggest that resistance to conventional therapy could be determined at the endothelial level." (PMID 19650939, 2009). "However, the associations of NOS3 polymorphisms with hypertension and the response to multicomponent physical training remain unclear." (PMID 33790801, 2021). "In particular, two hypertension related mutations were identified; a homozygous risk factor rs699 locus was found to have a missense functional class causing an amino acid change (M268T) and a heterozygous risk factor rs1799983 locus in the NOS3 gene casing an amino acid change (D298E)." (PMID 31604968, 2019). "NOS3 (fetal and maternal-acting), NRK (fetal), and ADAMTS8 (maternal-acting) have been implicated in placental function and hypertension." (PMID 39809772, 2025). "A clinical study has shown the association of endothelial nitric oxide synthase (Nitric Oxide Synthase 3, NOS3) gene G894T polymorphism with hypertension risk and complications." (PMID 38732608, 2024). "NOS3, NRK, and ADAMTS8 (fetal and maternal-acting) have been implicated in both placental function and hypertension." (PMID 38633783, 2024). "For PC1, shared genetic variants with diastolic blood pressure (ATXN2, GOSR2, NOS3, BAG3) and hypertension (ATXN2, VEGFB, NOS3, BAG3) were also observed." (PMID 39543113, 2024). "The NOS3 (Nitric Oxide Synthase 3, Endothelial Cell) gene was identified to be involved in AD, dementia, Parkinson’s disease, and hypertension." (PMID 38790243, 2024). "Among NEMG, variants within Nitric Oxide Synthase 3 (NOS3) showed associations with CVD, CAD, hypertension, as well as diastolic and systolic blood pressure." (PMID 39258111, 2024). "One previous study reveals that STAT-1 is crucial in Nitric oxide synthase-3 (Nos-3) related hypertension and worsened periodontitis." (PMID 39376880, 2024). "The findings of our study place NOS3 as the gene most consistently associated with CVD, CAD and blood pressure related traits (hypertension, SBP and DBP)." (PMID 39258111, 2024). "Nos3-/- hypertension downregulates STAT3's anti-inflammatory function and downstream chemokine expression." (PMID 39219951, 2024). "Our results demonstrate the effect of adipocyte-specific NOS3 knockout in potentiation of HFD-induced hypertension, which directly supports the importance of NOS3 in adipocytes." (PMID 37897505, 2023). "Association studies have shown that heterozygous loss-of-function variants in NOS3 and GUCY1A3 genes were associated with an increased risk to develop hypertension and coronary heart disease." (PMID 36941667, 2023). "Strikingly, the deletion of adipocyte NOS3 led to an exaggeration of HFD-induced hypertension in the present study." (PMID 37897505, 2023).
Hypertension (continued). "A case-control study was conducted to evaluate the relationship between endothelial nitric oxide synthase (NOS3) gene polymorphism and essential hypertension in the Han, Miao, and Buyi populations in Guizhou China." (PMID 36758021, 2023). "In conclusion, ApoE/NOS3−/− adult mice are a satisfactory model of hypertension and atherosclerosis and can be utilized for studies on cardiovascular diseases." (PMID 36360235, 2022). "ApoE−/− mice had normal blood pressure levels, and ApoE/NOS3−/− mice exhibited hypertension-induced pathological changes." (PMID 36360235, 2022). "The focus of this study was to develop an atherosclerosis model with hypertension, and there have been few comparisons between ApoE/NOS3−/− and NOS3−/− mice." (PMID 36360235, 2022). "We established ApoE and NOS3 double knockout mice with typical clinical features of hypertension and atherosclerosis." (PMID 36360235, 2022). "ApoE/NOS3−/− mice can reach a blood pressure of 133.00 ± 3.85 mmHg in adulthood and suffer from hypertension." (PMID 36360235, 2022). "NFKB1 is involved in hypertension progression by affecting vascular endothelial function via the regulation of downstream NOS3 gene expression." (PMID 35655614, 2022). "This study aimed to investigate the prevalence of polymorphisms NOS3; rs1799983, IGFBP3; rs11977526 and TCF7L2; rs7903146 in Brazilian women of African descent and their association with hypertension." (PMID 34001234, 2021). "In our analysis, the dominant and recessive showed a strong association of TT and AA genotypes of the NOS3 and IGFBP3 genes, respectively, with hypertension." (PMID 34001234, 2021). "Multiple studies showed associations of single nucleotide polymorphisms in the NOS3 gene (that encodes for endothelial NOS) with vasospasm, hypertension, and cardiovascular death." (PMID 34945057, 2021). "In the case of hypertension, hypercholesterolemia, smoking and diabetes, and oxidative stress, the NOS3 cofactor is oxidized, which results in down regulation of aortic nitric oxide and antioxidant systems." (PMID 34202347, 2021). "Polymorphisms in the NOS3, DDAH1, DDAH2, and AGXT2 genes have previously been shown to relate to NO-mediated vascular function, hypertension, and mortality in a range of different patient populations." (PMID 34945057, 2021). "Brazilian Afro-descendant women with the TT genotype for the NOS3 gene and the AA genotype for the IGFBP3 gene are more susceptible to hypertension." (PMID 34001234, 2021). "The less frequent genotypes of the NOS3, rs1799983, TCF7L2 rs7903146, and IGFBP3 rs11977526, SNPs were associated with a higher prevalence of hypertension in comparison with the ancestral and heterozygous genotypes." (PMID 34001234, 2021). "For the NOS3, rs1799983 SNP, the prevalences of hypertension among women with GG, GT and TT genotypes were 24.5%, 23.0% and 52.0%, respectively, with a statistically significant difference between TT and GG (PR = 1.54; 95% CI 1.27–1.86; p < 0.001)." (PMID 34001234, 2021). "The aim of the review is to study the role of SNVs of the NOS1, NOS2, and NOS3 genes in the comorbidity of arterial hypertension and tension-type headache." (PMID 33809023, 2021). "Through the reduction of multifactorial dimensionality, it can be verified that there is a close and strong genotype interaction between ACE and NOS3 that in turn relates to hypertension as well as to hypercholesterolemia, smoking, and red meat intake." (PMID 32714484, 2020). "The strong redundant interactions of red meat consumption, smoking, BMI, and hypercholesterolemia are additive to high blood pressure, ACE, and NOS3 genotype polymorphisms, all being able to contribute to cardiovascular risk." (PMID 32714484, 2020). "STZ‐treated male and female Nos3‐/‐ mice maintained comparable hyperglycemia between weeks 3 and 8 had an equivalent increase in HbA1c levels and comparable hypertension." (PMID 31535473, 2019).
Hypertension (continued). "There is also evidence demonstrating significant associations between NOS3 894 polymorphisms and two leading risk factors of IHD, hypertension and type 2 diabetes in Asians." (PMID 30071659, 2018). "The single nucleotide polymorphism (SNP) NOS3 894GT located in exon 7 (also known as Glu298Asp, rs1799983) is a genetic marker that has been specifically linked to an increased risk of IHD, hypertension, coronary spasms, and stent re-stenosis." (PMID 30071659, 2018). "According to Li and colleagues, two regulatory genes, the C allele at rs2070744 of the NOS3 and the T allele of rs4961 of the ADD1 gene, are significantly associated with the high prevalence of hypertension among Tibetan patients." (PMID 25953970, 2015). "The univariate analysis showed that age, hypertension and NOS3 VNTR influenced the advancement of CKD." (PMID 25340172, 2014). "Stratified analysis further showed that the NOS3 VNTR was an effect modifier of the relationship between hypertension and CKD advancement among the ADPKD patients." (PMID 25340172, 2014). "Given the pivotal role of NO in vascular homeostasis, the endothelial nitric oxide synthase gene (NOS3) has emerged as a logical candidate gene in the investigation of hypertension genetics." (PMID 20981307, 2010). "Extensive research has underscored the involvement of macrophages in the pathogenesis of hypertension, primarily through the promotion of NOS3 uncoupling and the activation of excessive ROS generation, ultimately culminating in vascular oxidative stress and hypertension." (PMID 39223947, 2024). "For the first time, we present direct evidence demonstrating that the absence of adipocyte NOS3 leads to the exaggeration of diet-induced hypertension, which is associated with vascular dysfunction and remodelling." (PMID 37897505, 2023). "While it is probable that this variant impairs NOS3 expression by interfering with NOS3 promotor activation, these data indicate that dysregulation of AGAP3 may also contribute to the increased risk for systemic hypertension." (PMID 35999210, 2022). "Compared with ApoE−/− mice, ApoE/NOS3−/− mice showed more severe atherosclerosis, suggesting that hypertension may aggravate the process of atherosclerosis, and the underlying mechanism needs to be studied further." (PMID 36360235, 2022). "The restriction or promotion of NOS3 expression leads to unstable NO production and the damage and dysfunction of the vascular endothelium, leading to diseases, such as atherosclerosis and hypertension." (PMID 36360235, 2022). "The vascular function might be improved by inhibiting the activation of the NOS3-pathway, providing an experimental basis for the development of hypertension in Chinese medicine." (PMID 34055010, 2021). "Also, the synergistic interaction of the NOS3 endothelial enzyme genotypes, conditioning the activity of this enzyme, with the degree of arterial hypertension, denotes to be one of the relevant mechanisms in the microcirculatory preservation in longevity." (PMID 32714484, 2020). "Compounds (for example, Angustidine) targeting proteins in sub-modules (such as NOS2 and NOS3) may effect on both AD and hypertension." (PMID 29997503, 2018). "Furthermore, APOE, NOS3, ACE, AGT, and CYP variants influence the therapeutic response to hypotensive drugs in AD patients with hypertension." (PMID 29301387, 2018). "Mice that lacked the NOS3 gene that codes for eNOS had certain cardiovascular risk factors which appear to imitate human MetS including hypertension, metabolic insulin resistance, and hyperlipidemia." (PMID 29907847, 2018). "The potential contribution of NOS3 polymorphisms to the development of hypertension in Sudan has received no attention to date, and no previous studies have addressed this subject." (PMID 29132319, 2017).